SPP1 (secreted phosphoprotein 1)
Diseases named in the same sentence as SPP1 in open-access papers (continued):
Sharing a sentence is not in itself a finding about the gene and the disease.
melanoma (continued). "Our findings revealed that EEF2K/p‐STAT3/SPP1 might be a novel oncogenic pathway in melanoma progression and could serve as an important reference point for potential combination therapy for melanoma." (PMID 35184394, 2022). "EEF2K mediates melanoma progression through p‐STAT3/SPP1 axis." (PMID 35184394, 2022). "EEF2K/p‐STAT3/SPP1 may be a novel oncogenic pathway in melanoma progression, which could be a target for novel combination therapy for melanoma." (PMID 35184394, 2022). "We previously identified that BET inhibitors could suppress melanoma progression by downregulating SPP1 expression." (PMID 35184394, 2022). "Overexpression of SPP1 predicted poor prognosis in melanoma." (PMID 33052224, 2020). "The Oncomine database confirmed that SPP1 was overexpressed in melanoma compared to normal skin." (PMID 33052224, 2020). "To investigate whether SPP1 mediates the effect of BET inhibitors in melanoma, we stably overexpressed SPP1 in A375 cells." (PMID 33052224, 2020). "Mechanistically, BET inhibitors suppressed melanoma progression via the BRD4/NFKB2/SPP1 axis." (PMID 33052224, 2020). "Our findings suggested that SPP1 could act as a biomarker for the diagnosis and progression of melanoma." (PMID 33052224, 2020). "Overall, we identified SPP1 as a potential melanoma driver through bioinformatics analysis." (PMID 33052224, 2020). "However, SPP1 was identified as the only potential melanoma driver due to its high expression in metastatic melanoma, moderate expression in primary melanoma, and low expression in normal skin." (PMID 33052224, 2020). "NFKB2 silencing resembled the phenotype observed by BET inhibitors and SPP1 silencing in melanoma." (PMID 33052224, 2020). "More importantly, SPP1 expression was positively correlated with the pathologic grades of melanoma." (PMID 33052224, 2020). "Our study reanalyzed the GSE15605 and GSE46517 datasets, which included normal skin, primary melanoma and metastatic melanoma data and identified 70 DEGs as potential melanoma driver genes, among which increased SPP1 expression was detected in normal skin < primary melanoma < metastatic melanoma." (PMID 33052224, 2020). "Interestingly, SPP1, one of the most highly upregulated genes in melanoma progression, has also been shown to promote osteoclast survival by activating calcineurin-NFAT signaling through integrin binding via its RGD motif." (PMID 26918341, 2016). "The αvβ3 integrin receptor may also be activated by other ligands expressed by melanoma cells, such as SPP1, as we recently reported." (PMID 26918341, 2016). "Our group confirmed increased expression of SPP1 in primary tumours to be of independent prognostic value for melanoma using an agnostic approach; utilising the Illumina cDNA-mediated annealing, selection, extension and ligation (DASL) platform which measures expression of 502 cancer-related genes." (PMID 23934016, 2013). "Some studies of using high-throughout gene microarray have revealed several putative genes associated with melanoma metastasis, such as SPP-1, MITF, CITED-1, GDF-15, c-Met and so on, but none of them was tested the signature in clinical materials." (PMID 20701774, 2010). "Similarly, we examined 2 paired cell lines (MCC80a from a primary melanoma from a synchronous metastatic lymph node, MCC80b), showing a slight increase in SPP1 protein expression in the latter." (PMID 18442402, 2008). "Furthermore, we found that p‐STAT3 could bind to the promoter region of SPP1 and enhance transcription, thus facilitating melanoma progression." (PMID 35184394, 2022). "Thus, we examined the Xiangya melanoma cohort and found that SPP1 overexpression could predict the unfavorable survival of melanoma patients." (PMID 33052224, 2020). "Considering the role of SPP1 in melanoma, targeting SPP1 could be beneficial in melanoma therapy." (PMID 33052224, 2020). "We also found that SPP1 overexpression in melanoma was independent of key melanoma mutations." (PMID 33052224, 2020).
melanoma (continued). "Also, SPP1 overexpression could partially reverse the suppressive effect of BET inhibitors on melanoma." (PMID 33052224, 2020). "The expression of SPP1 (osteopontin), a regulator of epithelial-mesenchymal transition (EMT) and a characteristic of melanomas with high metastatic potential, was approximately ten-fold higher in our B16 variants compared with the parental B16-F0." (PMID 39819494, 2025). "Our data are supported by findings in osteosarcoma and melanoma, showing that HOXB9 and PBX1, respectively, contribute to SPP1 activation in these tumours." (PMID 40149711, 2025). "The LAMININ, FN1, ADGRE5, SPP1, MK, CDH1, and APP signals mainly originated from melanoma cells and were received by multiple cell types, suggesting that melanoma cells play extensive roles in the ecosystem." (PMID 41357561, 2025). "Despite the known differences between mouse and human immune systems, one of these markers, SPP1, was also induced by POSTN both in murine macrophages in culture and in intratumoral macrophages in a mouse melanoma model." (PMID 38942020, 2024). "As expected, TREM2+ TAMs from ESCC specifically expressed TREM2, SPP1, APOE, and three complement genes, consistent with TREM2+ TAMs from melanomas." (PMID 37187751, 2023). "It prompted the genes ITGA4, SPP1, and ITGB3 to promote the interactions between melanoma cells and the ECM and thus facilitated melanoma metastasis." (PMID 35054979, 2022). "Studies have also shown that SPP1 is an important target of BET inhibitors, which can effectively inhibit the growth of melanoma cells." (PMID 34771678, 2021). "A xenograft mouse model was used to investigate the effect of SPP1 and BET inhibitors on melanoma in vivo." (PMID 33052224, 2020). "Cell proliferation, wound healing, and Transwell assays were carried out to evaluate the effects of SPP1 and BET inhibitors in melanoma cells in vitro." (PMID 33052224, 2020). "Next, we treated A375 and SK-MEL-28 melanoma cells with different doses of NHWD-870 and obtained consistent results that SPP1 expression was inhibited in a dose-dependent manner." (PMID 33052224, 2020). "However, IHC showed more positive staining in primary melanoma than in nevi, implying that IHC could be used for monitoring SPP1 expression to differentiate nevi from melanoma while ELISA could be more appropriate to distinguish primary from metastatic melanoma." (PMID 33052224, 2020). "Here we identified secreted phosphoprotein 1 (SPP1) as a melanoma driver and a crucial target of BET inhibitors in melanoma." (PMID 33052224, 2020). "We then tested RUNT domain influence in driving melanoma cell migration to the bone by analyzing the expression of IBSP and SPP1 genes." (PMID 32204402, 2020). "Consistent with previous results, melanoma growth was inhibited by the BET inhibitor and promoted by SPP1 overexpression." (PMID 33052224, 2020). "Of the 185 melanoma patients, 158 had treated stage I–III, 17 had untreated stage III and 10 had untreated stage IV disease (median SPP1 level 54.7, 54.6 and 74.0 ng/ml, respectively)." (PMID 23934016, 2013). "In a melanoma dataset, we found that patients responding to Pembrolizumab or Nivolumab immunotherapy exhibited a higher signature score for SPP1 + SIRPα + macrophages than non-responders." (PMID 39696410, 2024). "Interestingly, many known melanoma-related genes like VEGF, SPP1, and CSF1 have been included in the 103 LR pairs selected by SpatialDM." (PMID 37414760, 2023). "Transfection‐induced re‐expression of SPP1 partly negated the inhibitory effect of EEF2K silencing on melanoma, whereas inhibition of SPP1 or STAT3 significantly abolished the efficacy of EEF2K on melanoma cells." (PMID 35184394, 2022). "We previously observed, in our high-throughput microarray-based gene expression study, that ulcerated melanomas exhibit 6-fold higher expression of the SPP1/OPN gene compared to non-ulcerated melanomas." (PMID 36091936, 2022).
melanoma (continued). "Moreover, melanoma samples from two independent cohorts (TCGA and GSE8401) also demonstrated significant up-regulation of SPP1 in metastatic versus primary melanoma samples." (PMID 33052224, 2020). "To identify drugs that suppress SPP1 in melanoma, we performed a pilot screening using vemurafenib (BRAF inhibitor), trametinib (MEK inhibitor), and NHWD-870 (BET inhibitor) and found that NHWD-870 inhibited SPP1 expression." (PMID 33052224, 2020). "Through drug screening, we found that BET inhibitors prevented SPP1 expression in a dose-dependent manner, and re-introduction of SPP1 could partially reverse the growth inhibition of BET inhibitors in melanoma." (PMID 33052224, 2020). "We assessed SPP1 expression in HEK-293T, HaCaT, and a panel of melanoma cell lines." (PMID 33052224, 2020). "In melanoma cells transcription factors c-Myb, AML-1a and C/EBPα bind to the SPP1 gene promoter and the transcription factor GLI1, a mediator of Hedgehog (HH) signalling have been shown to regulate SPP1 expression." (PMID 28030801, 2017). "SPP1 is a member of a group of EMT-related genes identified by comparing the expression profiles of melanoma samples from patients with and without distant metastases." (PMID 24586640, 2014). "For other genes, such as SPP-1, GDF15 (putative oncogenes), PITX-1 and CST6 (putative TSG), the major shifts in gene expression appear to occur at distinct but different times during the thickening of the primary melanoma tumors." (PMID 18442402, 2008). "However, the upstream regulatory mechanism of SPP1 and whether it enhances the inhibitory effects of BET inhibitors on melanoma remain largely elusive." (PMID 35184394, 2022). "Thus, our study highlights SPP1 as an essential target of BET inhibitors and has identified a novel mechanism by which BET inhibitors suppress melanoma progression via the noncanonical NF-κB/SPP1 pathway." (PMID 33052224, 2020). "In RUNT KO melanoma cells, reduced expression of genes involved in metastatic processes (e.g., CD31, MMP9 and VEGFA) was observed, and genes involved in promoting bone metastasis, such as IBSP (coding for bone sialoprotein) and SPP1 (coding for osteopontin), were downregulated." (PMID 32204402, 2020). "To explore whether the melanoma drugs could down-regulate SPP1 expression, we performed drug screening using vemurafenib, trametinib, or BET inhibitors and observed that the BET inhibitors suppressed SPP1." (PMID 33052224, 2020). "Interestingly, among the strongly repressed genes (67 genes, downregulated >8-fold, P<0.005) are insulin-like growth factor 1 (IGF1) and osteopontin (OPN, also named SPP1), two factors known to have anti-apoptotic, proliferative, and pro-invasive activity in melanoma." (PMID 23349796, 2013). "However, the role of SPP1 in melanoma and its regulation have not been studied well." (PMID 33052224, 2020). "We focused on macrophages and identified TREM2+ TAMs specifically expressing TREM2, SPP1, APOE, C1QC, C1QB, and C1QA, which were significantly upregulated in melanomas not responsive to ICB therapy." (PMID 37187751, 2023). "Past studies have also revealed that JQ1 can be used to treat vemurafenib-resistant melanoma cells and that BET inhibitors effectively suppress melanoma progression via the noncanonical NF-κB/SPP1 pathway." (PMID 34771678, 2021). "Among the most interesting, highly and significantly over-expressed genes in metastatic primary melanomas were TIMP1, VCAN, SPP1, and CTHRC1, all of which are expressed both by stromal fibroblasts and melanoma cells (data not shown)." (PMID 26918341, 2016). "As a result, SPP1 showed higher expression in brain cancer, bladder cancer, cervical cancer, CRC, esophageal carcinoma (ESCA), GC, HNC, kidney cancer, liver cancer, LC, lymphoma, melanoma, PCa and pancreatic cancer in comparison with non-carcinoma tissues." (PMID 33324676, 2020).
melanoma (continued). "For example, a recent study showed that secreted phosphoprotein 1 (SPP1) expression can be a melanoma driver, and BET inhibitor NHWD-870 targets the BRD4 subunit and suppresses SPP1 expression and ultimately melanoma progression via the non-canonical NF-κB/SPP1 pathway." (PMID 36844227, 2023).
glioma (129 papers, 2000 to 2025). A benign or malignant brain and spinal cord tumor that arises from glial cells (astrocytes, oligodendrocytes, ependymal cells). "Overall, the findings demonstrated that SPP1/HMOX1 were associated with poor overall survival in glioma patients, indicating their potential as clinical prognostic and therapeutic targets of oncolytic virus treatment." (PMID 40495644, 2025). "The results from GSEA enrichment indicated that elevated expression of SPP1/HMOX1 was strongly associated with glioma malignancy." (PMID 40495644, 2025). "The high expression level of SPP1 is associated with increased macrophage infiltration and worse prognosis in glioma." (PMID 40495644, 2025). "As high‐grade gliomas overexpressing SPP1/HMOX1 is associated with tumour progression and increased malignancy grade, genes co‐expressed with SPP1 and HMOX1 appear to be strongly associated with glioma development." (PMID 40495644, 2025). "TAMs are well known to promote glioma cell survival and angiogenesis, and SPP1+ TAMs have been implicated in tumour progression via their interaction with β1 integrin." (PMID 40395129, 2025). "The expression levels of SPP1/HMOX1 were significantly increased in glioma and associated with histological classifications and WHO grades." (PMID 40495644, 2025). "Consistent with the findings in human gliomas, Spp1, Aif1 and Ccl3 mainly expressed in glioma-associated macrophages, hemostatic microglia and activated microglia, respectively." (PMID 38515213, 2024). "SPP1 was a potential biomarker of glioma risk and was involved in the proliferation, invasion, and angiogenesis of glioma cells." (PMID 36035133, 2022). "SPP1 was overexpressed in the high-risk group of glioma patients and was correlated with poor prognosis." (PMID 36035133, 2022). "Expression levels of risk factors BRCA1, DNM1L, RCN1, HSPB1, RPN2, LRRK2 and SPP1 in high‐grade gliomas were greater than those in lower‐grade gliomas, while the protein expression levels of protective factor PDIA3 were exactly the opposite." (PMID 33611848, 2021). "We identified two αvβ3/αvβ5 integrin ligands, namely SPP1 and lactadherin, as glioma-derived factors responsible for polarization of glioma-associated microglia and macrophages (GAMs) into tumor-supporting cells." (PMID 32019108, 2020). "In a mouse model of PDGFB-driven glioma, Spp1 was the most up-regulated gene in tumor-associated astrocytes of the perivascular niche as compared to normal brain astrocytes." (PMID 32019108, 2020). "For example, SPP1 (also known as osteopontin) is known to promote glioma progression by regulating GBM-associated macrophage infiltration, while IGFBP3 impairs T cell accumulation in breast cancer." (PMID 31477638, 2019). "Transcriptomic data showed that Spp1 was up-regulated specifically in glioma-associated astrocytes compared to normal astrocytes in murine PDGFB-driven gliomas and proneural human GBMs." (PMID 28030801, 2017). "The genes Gpnmb and Spp1 were two of the highest upregulated genes in our GAMs data set, clustered into the glioma-regulated (red) module, and have been implicated in immune-suppression (Gpnmb) or tumor cell invasion (Spp1) in peripheral tumors." (PMID 25658639, 2015). "Apart from the M1/M2 gene analysis, we demonstrate that the expression of Gpnmb and Spp1 is highly upregulated in both murine and human glioma-associated microglia/macrophages." (PMID 25658639, 2015). "Furthermore, SPP1 is highly expressed in glioma-associated microglia in mice and humans, where high expression of SPP1 is associated with poor prognosis." (PMID 35953545, 2022). "As previous studies have postulated that SPP1 or osteopontin mediates infiltration of tumor-associated macrophages that promote the pro-tumorigenic potential of adjacent glioma stem cells (GSCs), we speculate that microenvironment interactions shape female GBM progression." (PMID 38491408, 2024).
glioma (continued). "In summary, the study identified that oncolytic virus VSV‐M51 treatment downregulated SPP1/HMOX1 expression in glioma cells." (PMID 40495644, 2025). "Our study elucidated an intricate association between SPP1/HMOX1 and multiple co‐expressed proteins in glioma, highlighting the potential role of SPP1/HMOX1 in regulating cell cycle and growth via the PI3K/AKT, JAK–STAT and syndecan 1 signalling pathways." (PMID 40495644, 2025). "To delve deeper into the mechanisms underlying gene interactions, we employed a single‐gene differential expression analysis to determine potential co‐expressed genes that strongly correlated with SPP1/HMOX1 in glioma." (PMID 40495644, 2025). "The results revealed that there are significant positive correlations between SPP1 and functional status in glioma, including EMT (correlation R = 0.57), metastasis (correlation R = 0.54) and invasion (correlation R = 0.48)." (PMID 40495644, 2025). "We demonstrate that a designer 7aaRGD peptide that blocks SPP1/integrin signaling prevents the emergence of immunosuppressive GAMs, and normalizes the tumor vasculature in experimental gliomas." (PMID 40281508, 2025). "SPP1 knockdown significantly inhibited the proliferative capacity of glioma cells in vitro, compared to the NC group (p < 0.05, p < 0.01)." (PMID 40495644, 2025). "Congruently, SPP1 was shown to recruit GAMs to mouse gliomas via αvβ5 integrin, and systemic administration of osteopontin-eliminating aptamers increased the median survival time of tumor-bearing animals by 68%." (PMID 40281508, 2025). "The integrin-blocking peptide (7aaRGD) was designed to block the binding of glioma-derived SPP1 and MFGE8 to αvβ3/αvβ5 integrins." (PMID 40281508, 2025). "The downregulation of SPP1 was confirmed to be significant in the two glioma cell lines (p < 0.001)." (PMID 40495644, 2025). "Altogether, these findings position SPP1+ TAMs as critical regulators of the glioma immune landscape." (PMID 40395129, 2025). "We previously identified two glioma-derived αvβ3/αvβ5-integrin receptors ligands, osteopontin/secreted phosphoprotein 1 (SPP1) and lactadherin/milk fat globule-epidermal growth factor 8 (MFG-E8), as activators of myeloid cell reprogramming in gliomas." (PMID 40281508, 2025). "The level SPP1 expression correlates with glioma malignancy grade and the level of macrophage infiltration." (PMID 40191211, 2025). "We subsequently evaluated the mRNA expression in a cohort of 20 glioma tissues using RT‐qPCR and found that SPP1 or HMOX1 was significantly overexpressed in glioma compared with non‐tumour tissues (p < 0.001)." (PMID 40495644, 2025). "Silencing of Spp1 or Mfge8 expression in glioma cells prevented GAMs accumulation and reduced tumor growth in orthotopic rat gliomas." (PMID 40281508, 2025). "To evaluate the prognostic significance of SPP1/HMOX1 overexpression in glioma specimens, we conducted Kaplan–Meier survival analysis." (PMID 40495644, 2025). "Further, in‐depth experimental validation studies are warranted to elucidate the mechanism of SPP1/HMOX1‐involved signalling pathways in glioma, and also to study their possible role and interrelation in cell migration and tumour metastasis." (PMID 40495644, 2025). "In line with the cell viability results, a significant increase in the apoptotic ratio was observed in glioma cells after si‐SPP1 transfection, as shown by Annexin V/PI staining analysis (p < 0.05, p < 0.001)." (PMID 40495644, 2025). "To elucidate the molecular mechanism by which SPP1/HMOX1 contribute to glioma development, we utilised TCGA‐GBMLGG data cohorts to carry out GSEA analysis." (PMID 40495644, 2025). "The data from TCGA analysis showed that the expression levels of SPP1/HMOX1 were higher in WHO Grade IV (GBM) tissues than in the low‐grade glioma (LGG) group." (PMID 40495644, 2025).